KLF2 (KLF transcription factor 2)
Diseases named in the same sentence as KLF2 in open-access papers (continued):
Sharing a sentence is not in itself a finding about the gene and the disease.
KLF2 also shares sentences with these, for which no sentence is quoted: acute lung injury (2 papers); acute myocardial infarction (2); aortic aneurysm (2); colitis (2); endometrial cancer (2); Lung Injury (2); lymph node metastasis (2); Myocardial fibrosis (2); osteoporosis (2); abdominal aortic aneurysm (1); acute lymphoid leukemia (1); acute pancreatitis (1); American trypanosomiasis (1); Anxiety (1); arterial disease (1); atopic dermatitis (1); autosomal dominant polycystic kidney disease (1); Chagas disease (1); chronic obstructive pulmonary disease (1); Cognitive impairment (1); colon adenocarcinoma (1); common variable immunodeficiency (1); dengue (1); diabetic retinopathy (1); diffuse large B-cell lymphoma (1); dilated cardiomyopathy (1); Ductal Breast Carcinoma (1); erythroleukemia (1); esophageal cancer (1); esophageal squamous cell carcinoma (1).
A further 32 diseases each share a sentence with KLF2 in 1 paper.